NR4A1 (nuclear receptor subfamily 4 group A member 1)
Diseases named in the same sentence as NR4A1 in open-access papers (continued):
Sharing a sentence is not in itself a finding about the gene and the disease.
colon carcinoma (continued). "Previous studies show that the C-DIM compounds DIM-C-pPhOH and DIM-C-pPhCO2Me bind NR4A1 and act as NR4A1 antagonists for transactivation assays in colon cancer cells and therefore these compounds were also used in this study on RMS cells." (PMID 27144436, 2016). "NR4A1 knockdown or treatment with the p-hydroxyphenyl-derived (DIM-C-pPhOH) NR4A1 antagonist in pancreatic, lung and colon cancer cell lines show that NR4A1 regulates at least three pathways that are important for cancer cell proliferation and survival." (PMID 26035713, 2015). "Moreover, in a colon cancer model, an NR4A1 antagonist decreased levels of NR4A1, Tox, Tox 2, and NFAT while increasing cytokine production in CD8+ T cells, suggesting that the overexpression of NR4A1 drives T cell exhaustion." (PMID 40508074, 2025). "The effects of DIM-3,5-Br2, DIM-3-CI-5-CF3 and DIM-3,5-CI2 on NR4A1- and NR4A2-dependent transactivation were determined in RKO, SW480 and HCT116 colon cancer cell lines transfected with GAL4-NR4A1 or GAL4-NR4A2 chimeras and UAS-Luc, which contains five yeast GAL4 response elements." (PMID 40332813, 2025). "Importantly, we found that I-NCMs were broadly effective in reducing cancer metastasis, as MDP treatment induced regression of established colonies of lung, breast, and colon cancers in WT and Nr4a1–/– hosts." (PMID 39545417, 2024). "The tumor growth inhibitory effects of CDIM/NR4A1 antagonists were observed in immune competent mice bearing MC-38 mouse colon cancer cells and this was accompanied by modest changes in CD8+ and CD4+ T-cells and Treg cells in TILs and a significant decrease in CD4+/CD8+ ratios." (PMID 37847301, 2023). "Future studies will also use CT26 mouse colon cancer cells and both orthotopic and genetic models of colon cancer to investigate the relative antitumorigenic effects of NR4A1 antagonists on tumors and immune cells and further develop optimal drug candidates for pre-IND and phase 1 clinical trials." (PMID 37847301, 2023). "Aberrant activated β-catenin signaling in colon cancer enhanced glycolysis; meanwhile, an NR4A1-β-catenin feed-forward loop happening in colon cancer cells proves from the side that NR4A1 may be involved in promoting glycolysis." (PMID 36052242, 2022). "NR4A1 translocation from the nucleus to the cytoplasm in colon cancer cells may initiate apoptotic cascades." (PMID 35600274, 2022). "DIM-C-pPhOH was initially characterized as an inhibitor of NR4A1-dependent transactivation and recent structure-binding studies demonstrate that DIM-C-pPhOH, DIM-C-pPhCO2Me and other C-DIMs bind the ligand binding domain of NR4A1 and exhibit NR4A1 antagonist activity in colon cancer cells." (PMID 27144436, 2016). "Moreover, we have also reported that this compound also inhibited tumor growth in a syngeneic mouse model of colon cancer using MC-38 cells as xenografts and the analysis of T cells in tumor-infiltrating lymphocytes showed that the dual NR4A1/2 ligands reversed T-cell exhaustion." (PMID 38540704, 2024). "Thus, NR4A1 antagonists decrease NR4A1-dependent pro-oncogenic activity and PD-L1 expression in colon tumors and inhibit NR4A1-dependent T-cell exhaustion in TILs and spleen and represent a novel class of mechanism-based drugs that enhance immune surveillance in tumors." (PMID 37847301, 2023). "However, NR4A1 has been reported to be overexpressed in multiple types of carcinomas in previous reports, and play a critical role in survival or cell proliferation in cervical, lymphoma, pancreatic, lung, and colon cancer cells." (PMID 33072067, 2020). "Limited data suggest that, like NR4A1, NR4A2 is also a pro-oncogenic factor in solid tumors, and in colon cancer, NR4A2 overexpression predicts an unfavorable prognosis and chemoresistance." (PMID 40332813, 2025). "In this study we show that like other NR4A1 inverse agonists piperlongumine inhibited RKO, SW480 and HCT116 colon cancer cell growth migration and invasion and induced apoptosis." (PMID 37808182, 2023).
colon carcinoma (continued). "In many solid tumors NR4A1 is overexpressed including lung, breast, ovarian, and colon cancer, and NR4A1 is also a negative prognostic factor for patient survival." (PMID 38116863, 2024). "TILs from MC-38 cell-derived colon tumors and splenic lymphocytes exhibited high levels of the T-cell exhaustion markers including PD-1, 2B4, TIM3+ and TIGIT and similar results were observed in the spleen, and these were inhibited by NR4A1 antagonists." (PMID 37847301, 2023). "In contrast, NR4A1 is overexpressed in most solid tumors and is a negative prognostic factor for lung, breast and colon cancer patients and knockdown studies show that NR4A1 plays a role in cancer cell proliferation, survival, migration and invasion." (PMID 27144436, 2016). "Similar results were observed in both RCC cell lines after treatment with DIM-C-pPhOH or DIM-C-pPhCO2Me, confirming that the NR4A1 antagonists inhibited NR4A1-regulated expression of survivin, bcl-2 and EGFR in ACHN and 786-O cells as previously reported in pancreatic, lung and colon cancers." (PMID 26035713, 2015). "NR4A1 is overexpressed in colon tumors and is a negative prognostic factor for patient survival." (PMID 40332813, 2025). "In contrast, our previous studies in pancreatic, lung and colon cancer cells show that C-DIM/NR4A1 antagonists act on nuclear NR4A1 and do not induce nuclear export of the receptor [confirmed in RCC cells] and these compounds also decrease NR4A1-dependent transactivation." (PMID 26035713, 2015).
prostate carcinoma (36 papers, 2010 to 2025). A carcinoma that arises from epithelial cells of the prostate gland. "Prostate cancer cells treated with leptomycin B, which blocks nuclear export and apoptotic drugs, showed decreased cytochrome c release due to decreased Nr4a1 mitochondrial binding." (PMID 31683815, 2019). "NR4A1 expression or over-expression is detected in cancer cell lines and tumors and is higher in prostate cancer biopsy specimens than adjacent normal tissue." (PMID 29861853, 2018). "Nr4a1 knockdown significantly decreased apoptosis in prostate cancer cells." (PMID 31683815, 2019). "For example, the genes TRIB1, NR4A1, and NR4A2 are significantly upregulated in prostate cancer and can serve as biomarkers." (PMID 40167331, 2025). "Similarly, Nurr77 (NR4A1), an orphan member of the NR4A subfamily, which is highly expressed in advanced prostate cancer and characterized to promote prostate cancer invasion following ADT, can control the STAR transcription in mouse Leydig cells in either SF-1-dependent or -independent manner." (PMID 33750894, 2021).
acute myeloid leukemia (31 papers, 2010 to 2025). Acute myeloid leukemia (AML) is a group of neoplasms arising from precursor cells committed to the myeloid cell-line differentiation. "Recent studies have shown that NUR77, which encodes nuclear receptor subfamily 4 group A member 1, plays an important role in tumor suppression in acute myeloid leukemia." (PMID 34224300, 2021). "Moreover, NR4A1 is highly expressed in acute myeloid leukemia; when truncated protein-encoding for part of the N-terminal domain of NR4A1, the NR4A1 transcript variant still maintains the stability and activity of HIF-1α." (PMID 36052242, 2022). "For example, double knockout of Nr4a1 and Nor1 genes in mice causes acute myeloid leukemia (AML)." (PMID 28903348, 2017). "NR4A1 has additionally been reported to play a tumor suppressive role in certain acute myeloid leukemia (AML) patients." (PMID 40508074, 2025). "The dual NR4A1 and NR4A3 knockout mice rapidly develop acute myeloid leukemia, and in blood-derived cancers, NR4A1 and NR4A3 exhibit tumor suppressor-like activity." (PMID 40332813, 2025). "In contrast, genetic depletion of NR4A members [Nr4a3 (Nor1); Nr4a1 (Nur77)] promoted the development of lethal acute myeloid leukemia in mice, suggesting them as tumor suppressors." (PMID 37833991, 2023). "Especially, the loss of NR4A1 and NR4A3 in mice leads to the rapid development of lethal acute myeloid leukemia, indicating tumor suppressor-like activity for these receptors." (PMID 34209871, 2021). "Previous reports using NR4A1/NR4A3 double knock-out mice revealed a striking phenotype of early postnatal lethality arising from the development of acute myeloid leukaemia." (PMID 24223135, 2013). "In addition, NR4A1 exhibits cholesterol regulating function by interacting with LXR in acute myeloid leukemia." (PMID 36052242, 2022). "Null mutation of both NR4A1 and NR4A3 results in a cell-autonomous and transplantable acute myeloid leukemia (AML)-like disease characterized by proliferative expansion of hematopoietic stem cells and accumulation of undifferentiated myeloid blasts in non-hematopoietic tissues." (PMID 26938745, 2016). "NR4A1/NR4A3 knock-out mice rapidly develop lethal acute myeloid leukemia (AML) and reduced dosage of these genes, in mice, leads to a phenotype that recapitulates myelodysplastic syndrome (MDS), a hematologic disorder with increased susceptibility to AML." (PMID 33330042, 2020). "In acute myeloid leukemia, DDA also partly activates LXR to increase NR4A1, further inhibiting the expression level of cholesterol biosynthesizing enzyme 3β-hydroxysterol-Δ8,7-isomerase (D8D7I), leading to cancer autophagy induction." (PMID 36052242, 2022). "NR4A1 and NR4A3 are silenced in human acute myeloid leukemia (AML), and abrogation of both genes in mice leads to rapid postnatal development of AML." (PMID 24086717, 2013). "Individually, both NR4A1 and NR4A2 exhibit pro-oncogenic activity in many solid tumors, whereas in many blood-derived cancers, NR4A1 and NR4A3 are classified as tumor suppressors based on the rapid development of acute myeloid leukemia observed in double knockout NR4A1−/−:NR4A3−/− mice." (PMID 38540704, 2024). "The function and mechanism of action of NR4A1 in cancer cells is complex; transgenic mice in which both NR4A1 and NR4A3 (Nurr1) have been knocked out rapidly develop an acute myeloid leukemia (AML) type of leukemia and there is evidence that NR4A1 is a tumor suppressor for AML." (PMID 27144436, 2016). "Knock-out mice without NR4A3 (Nor-1) and NR4A1 (Nur77) developed spontaneous acute myeloid leukemia suggesting tumor suppressing effects." (PMID 24528603, 2014). "Interestingly, knockout mice that are null for both NR4A1 and NOR1 develop acute myeloid leukaemia due to abnormal myeloid cell proliferation and apoptosis." (PMID 20642837, 2010).
acute myeloid leukemia (continued). "Modulation of NR4A receptor activity can influence disease outcome, as demonstrated in acute myeloid leukemia (AML), with the identification of specific drugs that modulate NR4A1/3 expression and NR4A-gene signatures in AML cells." (PMID 35935773, 2022). "NR4A3 is a key tumor suppressor in myeloid malignancy, mice lacking both NR4A1 and family member NR4A3 rapidly develop lethal acute myeloid leukemia (AML)." (PMID 33330042, 2020).
pancreatic cancer (31 papers, 2014 to 2025). "Survivin was first characterized as an NR4A1/Sp1-regulated gene in pancreatic cancer cells followed by characterization of β1-integrin as an NR4A1/Sp1 regulated gene in breast, pancreatic and colon cancer cells." (PMID 39858066, 2025). "NR4A1 regulates endoplasmic reticulum stress and Reactive oxygen species (ROS) levels in pancreatic cancer cells to promote cell proliferation and survival." (PMID 40666103, 2025). "The flavonoid-derived (chalcone) natural product broussochalcone induced apoptosis/ER stress in pancreatic cancer cells however the NR4A1 nuclear or extranuclear mode of action of this compound was not reported." (PMID 38116863, 2024). "We also examined the effects of flavone and the hydroxyflavones on NR4A1-dependent transactivation in Panc1 pancreatic cancer cells transfected with GAL4-NR4A1/UAS-luc constructs." (PMID 37175855, 2023). "In a previous study, we demonstrated that fangchinoline (FCN), a natural inhibitor of nuclear NR4A1, induces NR4A1-dependent apoptosis in human pancreatic cancer cells." (PMID 35563670, 2022). "The orphan nuclear receptor 4A1 (NR4A1) is highly expressed in human pancreatic cancer cells and exerts pro-oncogenic activity." (PMID 35563670, 2022). "Our previous research has identified FCN as an inactivator of NR4A1-mediated responses and showed that treatment of pancreatic cancer cells with FCN was highly effective at inhibiting cell growth and survival." (PMID 35563670, 2022). "NR4A1 also complexes with Sp1 and p300 on the region of survivin promoter to increase pancreatic cancer cell proliferation and decrease apoptosis." (PMID 36052242, 2022). "Previous studies have shown that NR4A1 is highly expressed in various types of human tumors, including pancreatic tumor, and plays an important role in tumor growth and metastasis." (PMID 33923503, 2021). "They further found that FBW7 activates ferroptosis and ultimately inhibits the proliferation of pancreatic cancer cells by regulating nuclear receptor subfamily 4 group A member 1/stearoyl-CoA desaturase 1(NR4A1/SCD1)." (PMID 34503532, 2021). "Recently, BCA was reported to be an inhibitor of the orphan nuclear receptor, NR4A1, and induces programmed cell death in pancreatic cancer cells." (PMID 34745413, 2021). "In this study, we identified broussochalcone A (BCA) as a new NR4A1 inhibitor and demonstrated that BCA inhibits cell growth partly by inducing NR4A1-mediated apoptotic pathways in human pancreatic cancer cells." (PMID 33923503, 2021). "Recent studies have demonstrated that BCA inhibits the orphan nuclear receptor, NR4A1, and induces apoptosis in pancreatic cancer MiaPaCa-2 and Panc-1 cells." (PMID 34745413, 2021). "The close 4-chlorophenyl analog 3f selectively activated NR4A2 (Nurr1) in pancreatic cancer cells and had only marginal effects on NR4A1 and NR4A3 activity." (PMID 35582221, 2020). "In human pancreatic cancer cells, fangchinoline inhibited cell proliferation and induced apoptosis, in part through the NR4A1-dependent pro-apoptotic pathways." (PMID 30301146, 2018). "C-DIM and DIM-C-pPhOH were found to bind and inactivate nuclear receptor (NR4A1) and also act as a NR4A1 antagonist in lung and pancreatic cancer cells." (PMID 27447608, 2016). "In addition, NR4A silencing and treatment with NR4A1 inactivators induced apoptosis in pancreatic cancer cells and tumors." (PMID 35563670, 2022). "However, since two novel pro-survival mechanisms of NR4A1 in pancreatic cancer cells have been identified, many studies have focused on the genomic functions of NR4A1 in cancer." (PMID 35563670, 2022). "Recently, a series of bis-indole-derived analogs (CDIMs) that bind to the LBD of NR4A1 and act as NR4A1 antagonists have been developed, and treatment with several CDIMs have been shown to inhibit the NR4A1-regulated pro-oncogenic responses in multiple cancer cells including pancreatic cancer." (PMID 35563670, 2022).
pancreatic cancer (continued). "Therefore, compounds that inactivate nuclear NR4A1 have been characterized as a new class of chemotherapeutic agents for the treatment of NR4A1 overexpression in pancreatic cancer." (PMID 33923503, 2021). "The orphan nuclear receptor 4A1 (NR4A1) is overexpressed in pancreatic cancer and exhibits pro-oncogenic activity, and NR4A1 silencing and treatment with its inactivators has been shown to inhibit pancreatic cancer cells and tumor growth." (PMID 33923503, 2021). "It has been shown in several studies that the orphan nuclear receptor subfamily 4 group A member 1 of the nerve growth factor IB (NR4A1) is over-expressed in human pancreatic cancer, and antagonizing this receptor promotes apoptosis and inhibits pancreatic tumor cell growth." (PMID 30301146, 2018). "NR4A1 showed coordinate regulation with redox sensitive genes, e.g., TXNDC5, suggesting NR4A1 may regulate oxidative stress as has been observed in pancreas cancer models." (PMID 25538889, 2014). "For example, the orphan nuclear receptor NR4A1 (Nur77) played a role in suppressing hepatocellular carcinoma by inducing a glycolysis to gluconeogenesis switch, whereas it facilitated cancer cell proliferation via the ROS/endoplasmic reticulum stress pathways in pancreatic cancer." (PMID 30867652, 2019). "Interestingly NR4A2 also regulates autophagy and DIM12 decreases ATG7 and ATG12 gene expression in pancreatic cancer cell and tumors, whereas celastrol induced NR4A1-dependent autophagy, demonstrating opposing effects of NR4A1 and NR4A2 ligands which may also be cell context dependent." (PMID 38116863, 2024). "In conclusion, TTD is a natural ligand of NR4A1 that acts as an antagonist, and treatment with TTD inhibited pancreatic cancer cell growth in both cell culture and in vivo studies in part through the regulation of two NR4A1-dependent apoptotic pathways." (PMID 35563670, 2022). "The pro-oncogenic NR4A1-regulated activities have previously been characterized in colon, lung and pancreatic cancer cells, and the C-DIM/NR4A1 antagonists inhibited these pathways and gave results comparable to those observed for RNA interference (RNAi)." (PMID 27144436, 2016). "In this study, we evaluated FCN and its structural analogs (berbamine, isotetrandrine, tetrandrine, and tubocurarine) for their inhibitory effects on NR4A1 transactivity, and confirmed that tetrandrine (TTD) showed the highest inhibitory effect in pancreatic cancer cells." (PMID 35563670, 2022). "The comparable effects observed in vivo and in vitro demonstrated that TTD is an NR4A1 antagonist that acts as an antagonist to inhibit NR4A1-dependent pro-oncogenic pathways, and this confirms a potential clinical role for TTD as another NR4A1 antagonist in pancreatic cancer chemotherapy." (PMID 35563670, 2022). "NR4A1 is known to suppress ROS-mediated ER stress by maintaining low levels of oxidative stress, and previous studies also showed that DIM-C-pPhOH induced apoptosis via the ROS/ER stress-mediated pathway in pancreatic cancer cells." (PMID 35563670, 2022). "In this study, we identified a new NR4A1 inactivator, broussochalcone A (BCA), through screening a herbal medicine-derived small molecule library, which showed that BCA induces NR4A1-dependent apoptosis in human pancreatic cancer cells." (PMID 33923503, 2021).
colorectal cancer (30 papers, 2010 to 2025). A primary or metastatic malignant neoplasm that affects the colon or rectum. "For example, in colorectal cancer, overexpressed NR4A1 promoted cancer cell growth, epithelial-mesenchymal transition (EMT), and cancer stem-like cells (CSCs) properties." (PMID 36052242, 2022). "After silencing NR4A1AS in colorectal cancer cells, the NR4A1 mRNA bound to UPF1 was seen to almost double." (PMID 33732285, 2021). "The upregulation of lncRNA NR4A1AS expression in colorectal cancer tissue is positively correlated with the expression of NR4A1 mRNA." (PMID 33732285, 2021). "Two groups showed that Nr4a1 knock down in HCT116 colorectal cancer cells decreased growth and viability." (PMID 31683815, 2019). "Nr4a1 has also been specifically identified to induce proliferation in colorectal cancer, renal cancer, medulloblastomas and thyroid cancer." (PMID 31683815, 2019). "Quercetin and kaempferol have many of the same targets, such as AKT1, AHR, BCL2, NR4A1, etc., and AHR can inhibit the development of colorectal cancer 119-121." (PMID 37497415, 2023). "Interestingly, the expression of an antisense lncRNA against NR4A1, NR4A1AS, was shown to modulate NR4A1 expression in colorectal cancer cells." (PMID 38791553, 2024). "This suggests that in colorectal cancer, the combination of the two may promote the expression of AHR, inhibit the expression of NR4A1, and achieve the synergistic effect of inhibiting CRC." (PMID 37497415, 2023).